ENSG00000244255 (novel complement component 2 (C2) and complement factor B (CFB) protein)
Gene: Protein-coding gene on chromosome 6 (31,927,698 to 31,952,048, forward strand). Ensembl gene ENSG00000244255.
Genetic constraint (gnomAD): Loss-of-function variants: 106 observed, 166.08 expected, observed/expected ratio (o/e) 0.64, 90% interval 0.54 to 0.75. The synonymous counts are far from expectation, so gnomAD's model fits this gene poorly and the ratio says little. Missense variants: 1,332 observed, 1,687.6 expected, observed/expected ratio (o/e) 0.79, 90% interval 0.75 to 0.83. Synonymous variants: 525 observed, 632.3 expected, observed/expected ratio (o/e) 0.83, 90% interval 0.77 to 0.89.